VCP (valosin containing protein)
Diseases named in the same sentence as VCP in open-access papers (continued):
Sharing a sentence is not in itself a finding about the gene and the disease.
retinal degeneration (6 papers, 2010 to 2023). Degeneration of the retina. "In a fly model of adRP, inhibition of VCP or the proteasome alleviated retinal degeneration caused by Rh1P37H, despite the fact the clearance of misfolded RH1P37H was disrupted." (PMID 33137101, 2020). "These conflicting scenarios and the recent failure of autophagy induction to suppress Rh1RH27-mediated retinal pathology in Drosophila argue for additional studies to address the relevance of autophagy-promoting VCP activity to retinal degeneration caused by misfolded Rh." (PMID 20865169, 2010). "Is partial VCP inactivation able to protect against retinal degeneration in RhP23H-linked RP?" (PMID 20865169, 2010). "Our current work proves that pharmacological inhibition of VCP can also delay retinal degeneration in the RHO P23H rat in vivo." (PMID 33562020, 2021). "We show that inhibition of the VCP/proteasome activity favors cell survival and suppresses P23H-mediated retinal degeneration in RHOP23H rat retinal explants." (PMID 34680161, 2021). "This is consistent with our previous results, showing that inhibition of VCP function strongly attenuates retinal degeneration in flies as well as in rodent models of RHO P23H." (PMID 33562020, 2021). "In this study, we found that KUS121, one of the VCP modulators, effectively protects photoreceptors both morphologically and functionally, in two animal models of retinal degeneration, rd12 mice and RP rabbits with a rhodopsin (Pro347Leu) mutation." (PMID 27503804, 2016). "Despite this, Rh1P37H flies with decreased VCP function displayed a potent suppression of retinal degeneration and blindness, indicating that VCP activity promotes neurodegeneration in the Rh1P37H retina." (PMID 20865169, 2010). "Genetic inactivation of the ERAD retrotranslocator VCP increased the levels of misfolded Rh1P37H but surprisingly, conferred protection against Rh1P37H-mediated retinal degeneration." (PMID 20865169, 2010). "Using two doses of EerI (1 mM and 10 mM), we found that partial VCP/ERAD inhibition potently suppressed retinal degeneration in Rh1P37H;Rh1+/+ flies after 30 dle (n>7 flies/genotype)." (PMID 20865169, 2010). "It remained unclear, however, how the activity of VCP impacts on the RhP23H-mediated retinal degeneration and blindness." (PMID 20865169, 2010). "Pharmacological treatment of Rh1P37H flies with the VCP/ERAD inhibitor Eeyarestatin I or with the proteasome inhibitor MG132 also led to a strong suppression of retinal degeneration." (PMID 20865169, 2010). "Partial VCP inactivation rescued retinal degeneration and blindness in Rh1P37H flies; moreover, the rescuing effect of VCP inactivation also extends to another class II Rh1 mutation, ninaED1." (PMID 20865169, 2010). "VCP silencing led to a significant decrease of retinal degeneration." (PMID 33562020, 2021). "Indeed, VCP is required for autophagy flux, and blocking autophagy suppresses retinal degeneration in RhoP23H mice." (PMID 33137101, 2020). "Our finding that VCP inhibition rescues retinal degeneration in Rh1P37H;Rh1+/+ flies suggests that inhibition of the ERAD activity might exert long-term protective effects in Rh1P37H PNs." (PMID 20865169, 2010). "Thus, reducing VCP activity rescues retinal degeneration and blindness induced by a second class II mutant, ninaED1." (PMID 20865169, 2010). "Thus, VCP inactivation exerts a protective role on Rh1P37H-mediated retinal degeneration." (PMID 20865169, 2010). "Another substance found to attenuate retinal degeneration is ML240, which inhibits the valosin-containing protein (VCP), a potential therapeutic target for autosomal-dominant RP." (PMID 37111579, 2023). "Using an RNAi based approach, we now provide evidence, that silencing VCP expression in RHO P23H transgenic rat organotypic retinal cultures via Reverse Magnetofection can protect photoreceptor cell death and attenuate retinal degeneration in vitro." (PMID 33562020, 2021).
retinal degeneration (continued). "To investigate the relevance of Rh1P37H retrotranslocation and clearance to retinal degeneration, we focused our attention on the ERAD effector VCP/ter94/p97/cdc48, the driving force for extraction of misfolded proteins from the ER and delivery to the proteasome." (PMID 20865169, 2010). "First, the levels of VCP were found to be increased very early (after 1dle) in Rh1P37H-expressing flies, well before the onset of retinal degeneration; this suggests that VCP has no direct cell death-promoting activity." (PMID 20865169, 2010).
thyroid cancer (6 papers, 2021 to 2026). "Furthermore, examples of universal NIS trafficking mechanisms, e.g. ARF4 and VCP regulation, exist in both breast and thyroid cancer cells." (PMID 40748136, 2025). "We thus propose that VCP and related proteasomal pathways represent key targetable processes to modulate NIS function in thyroid cancer." (PMID 34520744, 2022). "The application of VCP inhibitors abrogated the inhibition of NIS function mediated by VCP and increased NIS expression at the plasma membrane followed by increased RAI uptake in thyroid cancer cells and primary thyrocytes isolated from a mouse model." (PMID 33995657, 2021). "Recently, VCP/p97 was shown to govern the proteolysis of sodium iodide symporter (NIS), which is necessary for iodide uptake and critical for the efficacy of ablative radioiodine (RAI) treatment of thyroid cancer." (PMID 34576340, 2021).
bladder cancer (5 papers, 2013 to 2024). "VCP also stabilized Beclin 1 and promoted autophagy in bladder cancer cells by downregulating ataxin-3." (PMID 37269429, 2023). "Our bioinformatics analysis and experimental data showed that the VCP protein level was significantly higher in bladder cancer tissues than in normal tissues." (PMID 37269429, 2023). "Co-IP confirmed that overexpression of circHIPK3 weakened the interaction of VCP and Beclin 1 in bladder cancer cells." (PMID 37269429, 2023). "The WB results showed that the expression of VCP in bladder cancer tissues was significantly higher than that in normal tissues (n = 15)." (PMID 37269429, 2023). "Overall, our results showed that the circHIPK3/VCP/Beclin 1 axis plays an important role in regulating the proliferation and autophagy of bladder cancer cells." (PMID 37269429, 2023). "Higher levels of VCP/p97 expression in patients with bladder cancer correlated with shorter survival following bladder removal by cystectomy." (PMID 34576340, 2021). "VCP inhibitors could effectively inhibit the expression of VCP, and the proliferation of bladder cancer cells and autophagy levels were also affected." (PMID 37269429, 2023). "Consistent with a previous study showing that inactivation or depletion of VCP delays the resolution of DNA DSBs in bone and bladder cancer cells following radiation-induced DNA damage, we observed a modest accumulation of DSBs upon loss of VCP, indicating accumulation of unrepaired DNA damage." (PMID 36923647, 2023). "However, there are few studies on the role of VCP in cancer, especially in bladder cancer." (PMID 37269429, 2023). "However, the role of VCP in cancer is still unclear, and whether VCP can promote autophagy levels by stabilizing Beclin 1 in bladder cancer is also unclear." (PMID 37269429, 2023). "This suggested that VCP may play the role of an oncogene in bladder cancer." (PMID 37269429, 2023). "We speculated that VCP may also rely on this pathway to regulate autophagy in bladder cancer." (PMID 37269429, 2023). "Thus, circHIPK3 may play an important role in bladder cancer by inhibiting VCP-mediated autophagy." (PMID 37269429, 2023).
cardiac hypertrophy (5 papers, 2017 to 2023). "For example, the protective effect of VCP/p97 on myocardial hypertrophy caused by ischemia–reperfusion injury and pressure overload is still controversial, studies are particularly required to understand its underlying molecular mechanisms." (PMID 33439255, 2021). "We previously reported that the valosin-containing protein (VCP), an ATPase-associated protein newly identified in the heart, acts as a significant mediator of cardiac protection against pressure overload-induced pathological cardiac hypertrophy." (PMID 33093614, 2020). "Since Akt is a central protein involved in many cellular processes in cardiac hypertrophy, further studies focusing on the relationship between VCP/p97 and Akt will help to further reveal the roles of VCP/p97 in cardiac hypertrophy." (PMID 33439255, 2021). "And overexpression VCP/p97 protects heart from cardiac hypertrophy, supported by the facts that VCP/p97 transgenic mice shown relatively normal cardiac structure and cardiac function compared with wild-type mice in the presence of cardiac pressure overload." (PMID 33439255, 2021). "Existing research suggests that VCP/p97 has a strong potential to be a new therapeutic target for ischemic-reperfusion injury and pressure overload-induced cardiac hypertrophy, although there remain some opposing views." (PMID 33439255, 2021). "Our previous study has shown that VCP attenuates pathological cardiac hypertrophy by selective inhibiting pressure-overload induced mTORC1/AKT/pS6 signaling." (PMID 33093614, 2020). "Our recent studies further indicate a strong link between the down-regulation of VCP expression and pressure overload-induced cardiac hypertrophy in chronic transverse aortic constriction (TAC) mouse model." (PMID 33093614, 2020). "Using RNA sequencing (RNA-seq), the present study aimed to elucidate the gene regulations conferred by the VCP involved in the protection against the pathogenesis of cardiac hypertrophy induced by TAC." (PMID 33093614, 2020). "In contrary, using a cardiac‐specific VCP TG mouse model, we further demonstrated that the increase in VCP in mouse heart significantly attenuated the pressure overload‐induced cardiac hypertrophy in vivo." (PMID 28799247, 2017). "Current research posits that VCP/p97 could emerge as a promising therapeutic target for ischemia-reperfusion injuries and pressure overload-induced cardiac hypertrophy, though there are dissenting perspectives that need further exploration." (PMID 38069058, 2023). "A recent study showed that overexpression of VCP/p97 did not alleviate the progression of myocardial hypertrophy caused by pressure overload." (PMID 33439255, 2021). "Moreover, we found that cardiac-specific overexpression of the VCP in transgenic mice (VCP TG) significantly attenuated the pathological cardiac hypertrophy compared to wild type (WT) mice." (PMID 33093614, 2020). "Based on the previous studies of the function of VCP in other cells, VCP may also protect against pathological cardiac hypertrophy via the regulation of ubiquitin–proteasome activity and autophagy." (PMID 28799247, 2017). "Given the decreased VCP level in hypertrophic hearts under pressure overload, we determined whether an increase of VCP expression prevents cardiac hypertrophy in vivo." (PMID 28799247, 2017). "However, the protective effects of VCP/p97 in myocardial hypertrophy remain controversial." (PMID 33439255, 2021). "As overexpressed VCP in VCP TG mice can restore the TAC‐induced reduction of VCP, the inhibition of pAKT T308 as well as its downstream mTORC1 signaling remains, preventing cardiac hypertrophy." (PMID 28799247, 2017). "These molecular data further suggest that VCP does not affect cardiac growth in normal condition but attenuates cardiac hypertrophy under TAC." (PMID 28799247, 2017).
cardiac hypertrophy (continued). "Under pressure overload, VCP expression was decreased in the hearts of WT mice and the inhibitory binding of VCP with AKT at T308 was removed, which allows AKT to become phosphorylated by PI3K/PDK1 on threonine 308, then subsequently activating mTORC1 signaling and inducing cardiac hypertrophy." (PMID 28799247, 2017).
lung adenocarcinoma (5 papers, 2015 to 2024). A carcinoma that arises from the lung and is characterized by the presence of malignant glandular epithelial cells. "The present study demonstrates that ER stress caused by disruption of VCP is associated with EMT in lung adenocarcinoma cells." (PMID 25970786, 2015). "Increased in Chop and Calnexin expressions, following loss of VCP in lung adenocarcinoma cells, were also confirmed by immunofluorescence staining." (PMID 25970786, 2015). "Importantly, we observed that VCP loss affects cell viability and colony forming ability of lung adenocarcinoma cells in concentration dependent manner." (PMID 25970786, 2015). "Thus, we determined whether loss of VCP in lung adenocarcinoma cells induces EMT by changing the expression levels of key EMT regulators." (PMID 25970786, 2015). "We previously showed role of AAA+ ATPase VCP, in the maintenance of the ER homeostasis in lung adenocarcinoma cells." (PMID 28186986, 2017). "We previously reported that either through siRNA mediated loss of AAA+ ATPase VCP or by its chemical disruption, cause ER stress and induces EMT in lung adenocarcinoma cells." (PMID 28186986, 2017). "We previously showed loss of AAA+ ATPase VCP is sufficient to cause endoplasmic reticulum (ER) stress, which ultimately induces EMT in lung adenocarcinoma cells." (PMID 28186986, 2017). "We observed ER stress after loss of VCP function, which was followed by EMT in lung adenocarcinoma cell lines." (PMID 25970786, 2015). "By examining primary lung adenocarcinoma patient samples we find that the VCP locus is heterozygously lost in nearly half of lung adenocarcinomas and VCP protein expression is decreased in nearly all primary lung tumors." (PMID 25970786, 2015). "Examination of primary clinical samples demonstrated that lung adenocarcinomas have decreased VCP expression, increased expression of ER stress markers and activation of EMT markers when compared to match normal adjacent tissues." (PMID 25970786, 2015). "Western blot analysis revealed that VCP protein is underexpressed in the vast majority primary lung adenocarcinomas, when compared to normal adjacent tissue." (PMID 25970786, 2015). "Additionally, the interaction between KRT80 and VCP plays a crucial role in the progression of lung adenocarcinoma, which implies that KRT80 is a promising therapeutic target." (PMID 38495507, 2024). "First, we knocked down VCP/p97 in A549 lung adenocarcinoma cells using stable inducible small hairpin RNAs (shRNAs) and quantified mRNA levels of BIP and CHOP as markers of the unfolded protein response (UPR) and integrated stress response (ISR), respectively, after glutamine or glucose depletion." (PMID 30626938, 2019). "Interestingly, we found that VCP loss by either methodology activated ER stress and induced EMT in lung adenocarcinoma cells." (PMID 25970786, 2015). "Moreover, analysis of TCGA data revealed that the VCP locus is lost in nearly 50% of lung adenocarcinoma samples." (PMID 25970786, 2015). "Furthermore, our study showed that the Src kinase inhibitor PP2 completely blocks ER stress and EMT induced by VCP inhibition in lung adenocarcinoma cells." (PMID 25970786, 2015). "Thus, we were interested to see the expression level of VCP in lung adenocarcinoma patients compared with matched normal adjacent tissues." (PMID 25970786, 2015). "Furthermore, we have demonstrated that ER stress, through loss of VCP, induced EMT in lung adenocarcinoma cell lines, suggesting a potential mechanism whereby ER stress may contribute to cancer progression through regulating EMT." (PMID 25970786, 2015). "We observed that sustained inhibition of VCP by either siRNA or EerI activated ER stress and induced EMT in lung adenocarcinoma cells." (PMID 25970786, 2015).
neuroblastoma (5 papers, 2013 to 2017). Neuroblastoma (NB) is the most common solid, extracranial childhood tumor. "The expression of these VCP cleavage fragments has been reported to impair degradation by the UPS system in neuroblastoma cells, but further studies are required before this pathway can be linked to the pathomechanism of TMD." (PMID 24618559, 2014). "To study VCP implication in mitochondrial function, we transiently silenced the VCP gene using siRNA in SH-SY5Y human neuroblastoma cells and shRNA in mouse primary cortical cultures." (PMID 23498975, 2013). "In this study, we used dynamic imaging techniques to explore the mitochondrial pathophysiology in a VCP knockdown (VCP KD) human dopaminergic neuroblastoma cell line (SH-SY5Y) and in fibroblasts from patients carrying three independent pathogenic mutations in the VCP gene." (PMID 23498975, 2013). "To investigate this further, we assessed mitochondrial coupling in stable VCP knockdown (KD) and scrambled (SCR) SH-SY5Y neuroblastoma cell lines." (PMID 28360103, 2017).
cognitive decline (4 papers, 2019 to 2025). "Two other patients carried Class-3 VCP variants: a 69 year old woman (P112), heterozygous for the missense p.Lys60Arg VCP variant, presented slowly progressive bulbar and limb muscle weakness and spasticity associated with cognitive decline." (PMID 32028661, 2020). "Further studies by ELISA and Peterson’s analyses validated that the upregulation of CIP2A, PRNP, and CRHBP and downregulation of VCP were indeed correlated to cognitive decline in T2DM patients." (PMID 36506101, 2022). "Further machine learning data showed that increases in PRNP, CRHBP, VCP, and rGSK-3β(T/S9) (ratio of total to serine-9-phosphorylated glycogen synthase kinase-3β) had the greatest power to identify mild cognitive decline in T2DM patients." (PMID 36506101, 2022). "Among them, the increases in PRNP, CRHBP, VCP, and rGSK-3β(T/S9) had the greatest power to identify cognitive decline in T2DM patients." (PMID 36506101, 2022). "By integrating proteomics and machine learning data, we identified that changes in PRNP, CRHBP, VCP, and rGSK-3β had the greatest power to identify cognitive decline in T2DM patients." (PMID 36506101, 2022). "The bioinformatics data together indicate that upregulation of SERPINA1, VCP, PRNP, CIP2A, HSPA9, and UQCRC2 and downregulation of IGFBP3, CRHBP, PEPD, and GUSB were correlated to cognitive decline in T2DM patients." (PMID 36506101, 2022).
cystic fibrosis (4 papers, 2010 to 2017). Autosomal recessive disorder caused by pathogenic variants in the CFTR gene (cystic fibrosis transmembrane conductance regulator), which encodes a chloride and bicarbonate channel expressed in epithelial cells, and follow the diagnosis criteria. "Increased ERAD/VCP activity leads to degradation of the cystic fibrosis-linked mutant ΔF508-CFTR, which retains some functionality despite being misfolded." (PMID 20865169, 2010). "Our group and others have previously discussed and reported the critical pathogenic role of VCP in neurological disorders, cystic fibrosis, chronic obstructive pulmonary disease (COPD) and various forms of cancers including NSCLC." (PMID 27434122, 2016). "The induction of VCP expression in chronic inflammatory states like cancer, cystic fibrosis and neurodegenerative conditions results in proteostasis-imbalance and pathogenesis of disease." (PMID 21085581, 2010). "As such, VCP/p97 is an attractive target in diseases involving excessive ERAD, such as cystic fibrosis and cancer." (PMID 28322292, 2017). "We found that VCP inactivation prevents neurodegeneration in Rh1P37H flies and VCP inhibition is also sufficient to rescue mutant CFTR from degradation and to partially restore CFTR function in a cellular model of cystic fibrosis." (PMID 20865169, 2010).
gastric cancer (4 papers, 2013 to 2022). A primary or metastatic malignant neoplasm involving the stomach. "To clarify the correlation between VCP expression and H. pylori-infected gastric cancer, we also assessed VCP expression level in vivo using a set of 22 samples from a cohort of 30 BALB/c mice." (PMID 23383273, 2013). "By identifying the interactome of VCP overexpressed in AGS cells using a subtractive proteomics approach, we aimed to characterize the cellular responses mediated by VCP and its functional roles in H. pylori-associated gastric cancer." (PMID 23383273, 2013).